PRKAA1-AS1 (PRKAA1 antisense RNA 1)
Gene: Long non-coding RNA gene on chromosome 5 (40,755,887 to 40,790,260, forward strand). Ensembl gene ENSG00000300383.
Gene Ontology:
Biological process: RNA processing
Cellular component: nucleolus